MUC1 (mucin 1, cell surface associated)
Diseases named in the same sentence as MUC1 in open-access papers (continued):
Sharing a sentence is not in itself a finding about the gene and the disease.
Pleural effusion (7 papers, 2008 to 2025). The presence of an excessive amount of fluid in the pleural cavity. "Malignant ascites and pleural effusion fluid demonstrated tumor cells positive for Muc1, Ber-EP4, TAG-72 and CEA (arrow) (n = 20)." (PMID 28489577, 2017).
serous ovarian carcinomas (7 papers, 2016 to 2024). "The chimeric RNAs generated from tripartite motif containing 46 (TRIM46) with MUC1 and KRTCAP2 have been clinically implicated in high-grade serous ovarian carcinoma." (PMID 34722520, 2021). "The expression of mucins (MUC16 and MUC1) and truncated O-glycans (Tn, STn and T) represents a characteristic footprint of serous ovarian carcinomas (SOCs)." (PMID 30011875, 2018). "MUC16 is known to be expressed in most serous ovarian carcinomas and may function like MUC1 and MUC4 in tumor cell growth, motility and tumorogenicity." (PMID 26735499, 2016). "In models combining mucin-1 (MUC1) and TnMUC1 CAR T cells with human high-grade serous ovarian cancer cell spheroids, malignant cell–intrinsic resistance to CAR T-cell killing was due to defective death receptor signaling involving TNFα." (PMID 38819641, 2024).
carcinosarcoma (6 papers, 2006 to 2025). A malignant tumor composed of a mixture of carcinomatous and sarcomatous elements. "Increased expression of MUC1 in malignant mammary gland tumours (carcinomas and carcinosarcomas) compared to its expression in benign mammary gland tumours and healthy gland tissue has also been observed in other studies." (PMID 40144054, 2025). "Strong MUC1 expression was observed in 99.1% ± 0.3% and 99.2% ± 0.2% of solid adenocarcinoma-derived cells and carcinosarcoma-derived cells, respectively." (PMID 40144054, 2025). "Cultures of both cell types exhibited strong positivity for MUC1 of >99% and high Ki-67 proliferation activity of 43.1% ± 0.5% in the solid adenocarcinoma-derived positive cells and 87.9% ± 2.7% in the carcinosarcoma-derived positive cells." (PMID 40144054, 2025). "Our current tumor population, however, also contains malignant mixed mesodermal tumors, also known as carcinosarcomas, endometrial stromal sarcomas, and adenosarcomas, which both contain an epithelial component where MUC1 is present." (PMID 27618037, 2016).
chronic kidney disease (6 papers, 2021 to 2025). Impairment of the renal function secondary to chronic kidney damage persisting for three or more months. "Hypoxia or pharmacological treatment with novel HIF stabilizers promotes the expression of MUC1 genetic variants that predispose to the development of chronic kidney disease in renal tubular cells." (PMID 37316299, 2023). "We used a targeted panel (29 genes) and MUC1-SNaPshot to sequence 271 DNAs, selected in defined disease entities and age cutoffs from 5217 individuals in the German Chronic Kidney Disease cohort." (PMID 36100708, 2022). "Taken together, our study links regulation of very common and very rare pathogenic variants of the kidney-disease gene MUC1 with the HIF pathway in renal tubular cells, which is activated in acute and chronic kidney disease and upon treatment with anti-anemic drugs." (PMID 37316299, 2023). "MUC1, located on chromosome 1q22, is a causative gene for autosomal dominant tubulointerstitial kidney disease (ADTKD), which is a hereditary disease characterized by progressive tubulointerstitial nephropathy that ultimately leads to end-stage renal disease (ESRD)." (PMID 34638981, 2021).
chronic pancreatitis (6 papers, 2005 to 2024). A chronic inflammatory process causing damage and fibrosis of the pancreatic parenchyma. "PDAC tissues were texturally uniform, demonstrating more homogenous expression of C595-reactive MUC1 compared to normal pancreatic and chronic pancreatitis tissues." (PMID 33379259, 2020). "Other studies revealed that MUC1 RNA levels are low in the tissue of both chronic pancreatitis and normal pancreas, while high MUC1 expression indicates the development of PC or PanIN progression." (PMID 32745356, 2020). "Our study demonstrated C595-reactive MUC1 expression in PDAC, with significantly lower expression in normal and chronic pancreatitis tissues." (PMID 33379259, 2020). "While MUC1, MUC4, and MUC5AC are the most differentially overexpressed mucins in human PDAC, the selective increase of MUC6 expression was identified as a potential biomarker for human chronic pancreatitis when compared to normal pancreas and PDAC in an unbiased screen." (PMID 25803032, 2015).
colorectal adenoma (6 papers, 2020 to 2026). An adenoma that arises from the colon or rectum. "The staining intensity of all anti-MUC1 Abs was stronger in squamous metaplasia tumors than in colorectal adenoma tumors." (PMID 36980805, 2023). "MUC1 has been reported to be highly expressed in human colorectal adenoma and adenocarcinoma, particularly at the advanced stage." (PMID 36980805, 2023). "Notably, several TAAs currently evaluated in clinical trials, such as EphA2 and Survivin for GBM and MUC1 for colorectal adenoma, are highly expressed in some normal tissues at the mRNA level without evidence for the induction of autoimmune responses." (PMID 41436600, 2026).
colorectal tumor (6 papers, 2006 to 2026). "Here, we demonstrated the preventive efficacy of the MUC1 DNA vaccine when combined with purified autologous bone-marrow-derived DCs (BMDCs) against a colitis-associated colorectal tumor in MUC1.Tg mice." (PMID 36980805, 2023). "The DNA vaccine targeting MUC1, a tumor-associated antigen, and autologous bmDCs was tested as a monotherapy in human MUC1 transgenic mice with colorectal tumors." (PMID 37886952, 2023). "This compares favourably with previous authors work, who also used the same semi-quantitative scoring system and found 32% and 43% MUC1 positivity in colorectal tumours respectively." (PMID 17349047, 2007). "We assessed the prognostic value of MUC1 on a larger set of colorectal tumours and included vascular invasion in our analysis to determine if MUC1 was truly independent as the previous studies have suggested." (PMID 17349047, 2007). "We have found MUC1 cytoplasmic tail and protein core expression in the plasma membrane, cytoplasm and nucleus in breast and colorectal tumor samples." (PMID 17064405, 2006). "We hypothesized that AOM-DSS treatment could induce MUC1-expressing colorectal tumor formation in MUC1.Tg mice." (PMID 36980805, 2023). "MUC1 is expressed in colorectal tumors, predominantly in those with more aggressive disease." (PMID 28153010, 2017). "A recent study has shown that the co-expression of MUC1 and nuclear beta-catenin at the invasion front of colorectal tumours may be correlated with a worse prognosis." (PMID 17349047, 2007). "The MUC1.Tg AOM-DSS carcinogenesis model provides high reproducibility and a simple mode of application and resembles human colorectal tumors in pathological and molecular aspects." (PMID 36980805, 2023). "We have therefore used TMA technology to analyze expression of MUC1 and MUC3 in a series of 462 paraffin embedded colorectal tumour specimens, in conjunction with a detailed data base of clinicopathological variables including disease specific survival." (PMID 17349047, 2007). "Correlation of MUC1 with poor prognosis has been reported in mismatch repair gene colorectal tumors but not in MLH1 negative tumors or in Lynch syndrome (HNPCC)." (PMID 28153010, 2017). "The results showed that although colorectal tumor formation could not be prevented completely, vaccination with MUC1 + BMDCs reduced the tumor incidence by 37.5% compared to the control." (PMID 36980805, 2023). "Therefore, we performed immunohistochemical analysis in non-vaccinated MUC1.Tg mice to confirm MUC1 expression in AOM-DSS-induced colorectal tumors by using anti-MUC1 antibodies (Abs) with different specificities." (PMID 36980805, 2023).
Crohn disease (6 papers, 2019 to 2025). A gastrointestinal disorder characterized by chronic inflammation involving all layers of the intestinal wall, noncaseating granulomas affecting the intestinal wall and regional lymph nodes, and transmural fibrosis. "In Crohn’s disease, the expression of mucin-1 (MUC1) in the inflamed epithelium at the terminal ileus suggests that the mucin cover is insufficient." (PMID 34261521, 2021). "The degree of methylation abnormality of MUC1 was negatively correlated with the disease activity score of Crohn's disease (r = − 0.50, P = 0.01)." (PMID 33963246, 2021). "The degree of abnormal methylation of MUC1 was negatively correlated with the disease activity of Crohn's disease." (PMID 33963246, 2021). "When examining gene expression of 130 known epithelial integrity genes we found no apparent trends toward altered expression in patients with controlled Crohn’s disease relative to controls including MUC1 and MUC4 which have previously been shown to remain dysregulated in controlled Crohn’s disease." (PMID 38830904, 2024). "In SAM enteropathy and in Crohn's disease there was increased expression of DUOX2, DUOXA2, lipocalin 2, CEACAM 5 and 7, MUC1, SAA 1, 2 and 4, and CXCL5 genes, and these transcripts were further over-expressed in HIV infection." (PMID 31229436, 2019). "By integrating multi-omics approaches, this study reveals a crucial connection between ferroptosis and immune microenvironment dysregulation in Crohn’s disease (CD), identifying seven hub ferroptosis-related differentially expressed genes (FEDGs): SCD, ATF4, SAT1, RPL8, MUC1, MTDH, and ATP6V1G2." (PMID 41515900, 2025).
gallbladder carcinoma (6 papers, 2012 to 2025). "Interestingly, the expression rate of stromal localization of sialylated MUC1 at the deepest invading sites of pT2 gallbladder carcinoma seems to be associated with a more frequent postsurgical peritoneal dissemination and lower survival rate of these patients." (PMID 32293552, 2020). "MUC1 expression is significantly higher in gallbladder carcinoma than in normal and inflammatory gallbladder epithelium." (PMID 23101681, 2012). "This study also observed high expression of MUC1 (81%) in gallbladder carcinoma." (PMID 23101681, 2012). "Regarding the prognostic value of MUC1 expression in gallbladder carcinoma, several studies described an association with a poor outcome in univariate analysis, but this study showed no relation between MUC1 expression and the outcome of patients with gallbladder carcinoma." (PMID 23101681, 2012). "The studies on MUC2 expression by gallbladder carcinoma showed that MUC2 expression is related to lower proliferative activity, contrary to MUC1 expression." (PMID 23101681, 2012). "The expression profiles of MUC4, MUC1, MUC2 mucins in gallbladder carcinoma tissues from 63 patients were investigated using immunohistochemical staining." (PMID 23101681, 2012). "For gallbladder carcinoma, positive staining of MUC4, MUC1, and MUC2 was 55.6%, 81.0%, 28.6%, respectively." (PMID 23101681, 2012). "In bile samples, WFA-sialylated MUC1 levels (nL/μg protein; median, range) were significantly higher in patients with either BTC or IhCC and patients with perihilar CC, distal CC, gallbladder carcinoma, and IhCC than in those with benign biliary tract diseases (7.4, 0.3–45)." (PMID 27358229, 2017).
gastric adenocarcinoma (6 papers, 2009 to 2025). "Here, analysis of the TCGA gastric adenocarcinoma dataset demonstrated that MUC1 expression is significantly increased in (i) GCs vs normal gastric tissues and (ii) EBVaGCs vs EBV-negative GCs without chromosomal instability (CIN) and microsatellite instability (MSI)." (PMID 40764753, 2025). "The expression level of Ras-related protein 31 (Rab31) is negatively correlated with the sensitivity of cisplatin to stomach adenocarcinoma, and it can activate Twist1 through regulating the Stats/Mucin 1 (MUC-1) signaling, thereby mediating cisplatin resistance and metastasis." (PMID 40052129, 2025).
gynecologic cancers (6 papers, 2011 to 2025). "This demonstrates the versatility of MUC1KrasPten mice in modeling, with high fidelity, immunobiology of MUC1 in gynecologic cancers." (PMID 25078979, 2014). "We also detected relevant surface biomarkers of these gynecological cancers, such as MSLN, MUC1, and CD276, in the PSOs and respective tumor tissues obtained from the same clinical samples." (PMID 38162496, 2023). "CTC presence analyzed with Adna Breast Test (detection of EpCAM-, MUC-1-, and HER-2-transcripts) together with CA 125 assessment were shown to be of prognostic significance in gynecological cancers." (PMID 21827674, 2011).
kidney cancer (6 papers, 2009 to 2024). Primary or metastatic malignant neoplasm involving the kidney. "Animal studies validated that Flex-Het inhibition of growth and induction of differentiation in association with upregulation of MUC-1 and E-Cadherin, and apoptosis also occurs in xenograft tumors generated from ovarian and kidney cancer cell lines." (PMID 35281109, 2022). "Nearly all human cancers, including over 90% of breast, pancreatic, ovarian, bladder, lung, and kidney cancers, and multiple myeloma, exhibit aberrant overexpression of MUC1." (PMID 38540735, 2024). "In summary, we report, in kidney cancer, that MUC1 is involved in cancer progression and sheddases ADAM10, ADAM17 and gamma-secretase are necessary for MUC1-C nuclear location and in increase of invasiveness." (PMID 24504508, 2014).
pancreatitis (6 papers, 2011 to 2025). Inflammation of the pancreas. "In summary, our results demonstrate that elimination of Muc-1 from all cell types in mice significantly reduces inflammation and severity of pancreatitis associated with CVB3 viral infection." (PMID 31337812, 2019). "Our results indicate that Muc-1 deficiency significantly attenuated the onset and severity of pancreatitis and decreased the degree of tissue damage that resulted from infection with CVB3." (PMID 31337812, 2019). "Our results suggest that molecular inhibition of these functions of Muc-1 offer a heretofore unexplored therapeutic avenue to reducing inflammation associated with pancreatitis." (PMID 31337812, 2019). "Immunohistochemistry was performed on primary and metastatic PDAC, pancreatitis, pancreatic intra-epithelial neoplasia and normal pancreatic tissue samples to identify potential changes in C595-reactive MUC1 expression across different disease groups." (PMID 33379259, 2020). "We aimed to extend this knowledge by also assessing C595-reactive MUC1 expression in benign pancreatic conditions such as pancreatitis and PanIN." (PMID 33379259, 2020). "The results presented here provide novel insight into the role of Muc-1 in regulating the inflammatory response and the cellular microenvironment in pancreatitis." (PMID 31337812, 2019). "We investigated the role of Muc-1 in early stages of a physiologically relevant model of enterovirus-induced pancreatitis." (PMID 31337812, 2019). "We elected to use this unique and physiologically relevant model of pancreatitis (infection with CVB3) to study the progression of early stages of pancreatitis, specifically to study the role of Muc-1 in this inflammation model." (PMID 31337812, 2019). "Muc-1 is involved in signaling through proinflammatory pathways that include NF-κB, and these pathways modulate inflammatory conditions in the microenvironment of the pancreas that influence the development of pancreatitis and also the progression of cancer." (PMID 31337812, 2019). "Another anti-MUC1 mAb was developed, PAM4, that shows high specificity for MUC1 expressed by PDAC compared to other cancers, normal pancreas or pancreatitis." (PMID 35892707, 2022). "Our observation that knockout of Muc-1 attenuates NF-κB expression and activation during CVB3-induced pancreatitis leads us to propose that Muc-1 is a signaling effector between EGFR and NF-κB." (PMID 31337812, 2019). "Each of the proteins MUC1, MUC5AC, and MUC16 showed significantly higher levels in the cancer patients than in the pancreatitis patients, both for early and late stage cancers." (PMID 22220206, 2011).
respiratory infection (6 papers, 2022 to 2023). "It has been demonstrated that MUC1 plays an important, pathogen-specific, and potentially multifaceted role during respiratory infection." (PMID 35699372, 2022). "Interestingly, MUC1 (mucin 1), a transmembrane mucin expressed by both epithelial and immune cells, has an immunomodulatory role to dampen inflammatory signaling during respiratory infection through direct interaction with toll-like receptors (TLRs)." (PMID 36829255, 2023). "Similarly, a higher viral titre was detected in Muc1−/− mice compared to WT mice in response to intranasal inoculation of murine adenovirus type 1 (MAV-1), suggesting that the Muc1 may protect against MAV-1 respiratory infections." (PMID 35774401, 2022).
silicosis (6 papers, 2017 to 2026). Silicosis is a respiratory disease caused by breathing in (inhaling) silica dust. "Deficiency of MUC1 exacerbates fibrosis progression in silicosis murine models, and MUC1 levels could be used to predict the severity of PF." (PMID 38914560, 2024).
thymoma (6 papers, 2015 to 2025). A neoplasm arising from the epithelial cells of the thymus. "In the diagnostic test accuracy review, MUC1 and beta-5t were found to be most useful in distinguishing between thymic carcinomas and thymomas in that meta-analysis." (PMID 35565429, 2022). "Ten markers, namely Podoplanin, Glut-1, Muc-1, Egfr, Igf1r, c-Jun, and n-Ras, from ten articles that included 748 cases of thymoma and 280 cases of thymic carcinoma were selected." (PMID 32993581, 2020). "MUC1 expression was significantly higher in TC than in B3 thymomas (94% vs. 0%), with a sensitivity of 94%, and may be a useful marker for differentiating TC from B3 thymomas." (PMID 41154432, 2025).
thyroid cancer (6 papers, 2009 to 2025). "CAR-NK cells specifically engineered to recognize mucin 1 (MUC1) have demonstrated improved cytotoxicity against ana-plastic thyroid carcinoma (ATC) cells and produced higher levels of IFN-γ, a key molecule that enhances the immune response against tumors." (PMID 40710340, 2025). "Accordingly, knockdown of MUC1 sensitises thyroid cancer cells to doxorubicine through activation of the intrinsic apoptotic pathway." (PMID 19672266, 2009). "In thyroid cancer, studies have found that MUC1, MUC4, and MU15 are overexpressed in PTC." (PMID 33489878, 2020). "In addition, a reduction in MUC1 proteins can increase chemotherapeutic sensitivity in thyroid cancer." (PMID 23708102, 2013). "Finally, another study used three epithelial tumour markers known to be overexpressed in thyroid cancer: B7H3/CD276, MUC1, and EpCAM." (PMID 41193833, 2025).